IL10 (interleukin 10)
Diseases named in the same sentence as IL10 in open-access papers (continued):
Sharing a sentence is not in itself a finding about the gene and the disease.
tumor (continued). "In contrast, M2 is supposed to participate in immunosuppression and tumor progression, which is formed after being exposed to the macrophage M-CSF, IL-10, IL-35 and the transforming growth factor-ß (TGF-β)." (PMID 37218976, 2023). "These cells can be converted into TAMs through soluble factors present in the tumor microenvironment such as IL-6, interleukin-10 (IL-10), interleukin-4 (IL-4), interleukin-13 (IL-13) and TGF-β57-60." (PMID 37215442, 2023). "Nevertheless, platinum-containing drug-based chemotherapy increases the probability of tumour cell lines inducing IL-10-producing M2 macrophages, which leads to poor antitumour metastasis activity and immunosuppression." (PMID 37537587, 2023). "A modest elevation of IL-10 secretion was seen in this study from macrophage interaction with C1GalT1-expressing tumour cells than with C1GalT1 suppressed cells." (PMID 37612278, 2023). "Human immune cells produce important cytokines such as IL-10 and increase the concentration of many cytokines within the ascites fluid emphasizing the impact of human immune cells on the tumor microenvironment." (PMID 36860657, 2023). "Found the HMOX1+ myeloid cells localized in the mesenchymal tumor area, which released IL-10 to drive T cell exhaustion." (PMID 36459212, 2023). "In consideration of the therapeutic application of IL-10, a half-life-extended form of IL-10 (pegylated IL-10) demonstrated effective tumor control in mouse models." (PMID 37586318, 2023). "It is essential to understand the regulatory mechanism of IL-10 in MPE formation, both for deciphering how IL-10 acts in regulating tumor immunity and for discovering important molecular targets for intervention in cancers." (PMID 37533789, 2023). "In contrast, M2 macrophages highly express the immunosuppressive factor IL-10, which exerts anti-inflammatory and tumor-promoting effects." (PMID 37151887, 2023). "MGL is superior to DC-SIGN in the ability to generate IL-10 producing regulatory T cells after DCs stimulation and is mainly investigated for its role in tumor immunology." (PMID 37006612, 2023). "Because of its immunosuppressive nature, IL-10 has also been suggested to be a factor leading to tumor cells’ evasion of immune surveillance and clearance by the host immune system." (PMID 38102207, 2023). "The poor outcome of GC is related to the infiltration of IL-10+ TAMs, which creates an immunoevasive tumor microenvironment in GC, resulting in the infiltration of regulatory T cells and dysfunction of the CD8+ T cells." (PMID 37291405, 2023). "The expression of IL-10 inhibits the activation of T cells and NK cells, leading to the proliferation and activation of tumor cells." (PMID 36979400, 2023). "Many stimuli have been reported in the literature, including IFN-γ, GM-CSF, and TNF-α inducing macrophages to M1 polarization for anti-tumor function, and IL-1β, IL-6, IL-10, and IL-4 inducing macrophages to M2 polarization for pro-tumor function." (PMID 37063892, 2023). "In tumor masses, microglia have native activity and can stimulate tumor growth by several cytokines and chemokines, such as IL-10, monocyte chemoattractant protein-1 (MCP-1/CCL2), some metalloproteinases (MMPs), and ARG1." (PMID 37170286, 2023). "They transform macrophages in tumor‐bearing individuals primarily by increasing IL‐10 production and decreasing macrophage‐derived IL‐12 production." (PMID 37547175, 2023). "Although the immunological role of IL-10 is relatively well understood, the clinical implications of IL-10 in the tumor microenvironment require further study." (PMID 37151396, 2023). "In contrast, M2 is supposed to participate in immunosuppression and tumor promotion, which are formed after being exposed to macrophage M-CSF, IL-10, IL-35 and TGF-β)." (PMID 37218976, 2023). "The complexity of IL-10’s mechanism of action in tumors has hindered the development of effective anti-tumor drugs targeting IL-10 and its signaling pathway." (PMID 37910571, 2023).
tumor (continued). "These cells along with tumor cells can also drive tumor growth and proliferation by secreting tumor facilitating cytokines, growth factors and chemokines including but not limited to IL-4, IL-10 and TGF-β." (PMID 36564524, 2023). "Due to a simultaneous stimulation by IL-2 and TGF-β, and the expression of the high affinity IL-2 receptor, T cells are more likely to differentiate into CD4+ Treg cells that protect the tumor by consuming IL-2 and secreting IL-10 and TGF-β." (PMID 37238744, 2023). "The IL secreted by TAMs, such as IL‐6, IL‐8, and IL‐10, can promote the proliferation and metastasis of tumor cells, as well as enriches the cancer stem cell population." (PMID 36794651, 2023). "IL-10 has been shown to suppress immune response, and this immunosuppression helps tumor cells to evade host immune clearance, thereby promoting proliferation and metastasis of cancer cells." (PMID 38102207, 2023). "IL-4, TGFβ and IL-8 were assessed in low amounts (471 to 820 pg/mg of tumor); CCL2, IL-12, IL-6 and IL-10 in moderate amounts (2825 to 3440 pg/mg of tumor); and IFNγ, TNFα, IL-1β and IL-2 in high amounts (6293 to 13,492 pg/mg of tumor)." (PMID 37526660, 2023). "According to studies, IL-10 has both pro-tumorigenic activity and activity in tumor inhibition through these functions." (PMID 37373957, 2023). "At the same time, CCL22 can further stimulate Treg to secrete IL-10, which can polarize macrophages to M2 type and promote tumor growth." (PMID 36969873, 2023). "The analysis of two independent cohorts of CLL B cells and PBMCs from a total of 97 patients demonstrated that CD5+CD19+CD27+ memory CLL B cells produce and secrete IL10 and TGFβ1, as part of the tumour cell secretome." (PMID 36973425, 2023). "Of these immune-related factors, the group with positive spontaneous IL-10 released from PBMCs had a significantly lower completion rate and a higher rate of tumor progression." (PMID 36672344, 2023). "In the macrophage-MG-63 co-culture, the IL-10/IL-6 ratio decreased under the effect of mifamurtide both in macrophages and in tumor cells." (PMID 37835437, 2023). "Regulatory T cells (Tregs) in the tumor microenvironment participate in the immunoregulation of cancer growth, producing immunosuppressive cytokines to support tumor growth, including interleukin-10 (IL-10)." (PMID 37894289, 2023). "The levels of iNOS and IL-10 were markedly increased in tumor-induced MDSCs, indicating their immunosuppressive function in cancer." (PMID 36969174, 2023). "Mounting evidences suggests the prime role of hypoxia in stimulating the secretion of cytokines and chemo- attractants from cancer cells and tumor associated macrophages, including CCL28, CCL22 and IL-10, that recruit Treg cells from the circulation." (PMID 37056346, 2023). "IL-10 is a pleiotropic immunosuppressive cytokine that can promote tumor metastasis; many immune cells produce IL-10." (PMID 37958430, 2023). "It is noteworthy that inflammatory cells can also produce cytokines that restrict tumor growth, such as IL-10 and IL-12, which lead to modulating apoptosis and suppressing angiogenesis." (PMID 38075864, 2023). "Alternatively, regulatory B cells (Bregs), dispersed inside the TME, contribute to the dampening of anti-tumor immune responses by secreting anti-inflammatory cytokines (IL-10 and IL-35), which promote tumor growth and metastasis." (PMID 37033931, 2023). "We observed a positive correlation of bacterial taxa, such as Corynebacterium, Prevotella, and the genus of Peptostreptococcaceae, with the expression of GATA3 (TH2) and IL-10, thereby suggesting their role as immunosuppressors in the tumor microenvironment." (PMID 37409975, 2023). "Conversely, IL-10 levels play an important role in the modulation of tumor progression: high levels of IL-10 in a tumor microenvironment block the activity of antigen-presenting cells (APC), cytotoxic T cells, and NK cells and stimulate tumor growth." (PMID 37409130, 2023).
tumor (continued). "An important aspect related to tumor immune escape is the secretion of factors with immunosuppressive activity: IL-10, TGF beta, IDO." (PMID 36986829, 2023). "The role of IL-10 in tumor pathogenesis is currently highly controversial, with some findings showing that IL-10 promotes tumor development and angiogenesis, while others supporting that it inhibits tumor growth and metastasis." (PMID 37359549, 2023). "β2AR signaling can also polarize macrophages from M1 to M2 type, thereby enhancing anti-inflammatory cytokines like IL-10, IL-4 & IL-13, and decreasing pro-inflammatory cytokines like INFγ, TNFα, IL1β, CCL2, CCL3 and CCL4 to cause tumor progression." (PMID 37006295, 2023). "We further examined the tumor samples from four treatment groups (control, IL-10-Fc, α-mCSF-1R, BF10)." (PMID 37586318, 2023). "M2 Macrophages in the microenvironment surrounding the tumor express a high level of IL10, which limits the tumor microenvironment’s immune response." (PMID 37894904, 2023). "The authors found out that, due to iNOS activity, the classic Th2 response was completely (IL‐4 and IL-13) or markedly (IL‐5, IL‐6, IL‐9, and IL-10) inhibited after tumor irradiation." (PMID 37347290, 2023). "The functional activity of NK cells can be suppressed by immunosuppressive molecules produced by immune cells in the tumor microenvironment and tumor cells, such as IL-10, TGFβ, and prostaglandin E2." (PMID 38248313, 2023). "Six out of 18 chemokines/cytokines assessed were significantly decreased in the ascites from NLRC5+ tumor-bearing mice, including IL-6, IL-10, IL-12, CXCL10, CCL5, and to a greater extent, CCL2." (PMID 38235131, 2023). "For example, tumour-associated macrophages (TAM) can enhance immunosuppression through transforming growth factor-β (TGF-β), secreting interleukin-10 (IL-10) etc., which is related to poor prognosis." (PMID 37691922, 2023). "IL-10 plays a key role in tumor immune evasion as well as its immunomodulatory functions with both immunosuppressive and immunostimulatory activities." (PMID 37533789, 2023). "M2-TAMs can directly stimulate tumor cell proliferation and invasion and suppress T cell recruitment and activation through the production of cytokines, such as interleukin (IL)-10 or epidermal growth factor (EGF)." (PMID 37402945, 2023). "Human interleukin-10 (IL-10) is an immunosuppressive and anti-inflammatory cytokine, and its expression is upregulated in tumor tissues and serum samples of patients with various cancers." (PMID 38102207, 2023). "The anti-inflammatory cytokine IL-10 can also unexpectedly stimulate tumor cell proliferation and migration." (PMID 37569777, 2023). "Regulatory B cells (Bregs) and IL-10-producing B cells (B10s) antagonize anti-tumor immunity through similar Treg-related mechanisms: IL-10, TGF-β and PD-L1 expression." (PMID 37108522, 2023). "IL-33 activates tumor-associated macrophages and dendritic cells by binding to its receptor, ST2, triggering the release of abundant Th2 cytokines, including IL-10, IL-4, and IL-13, which inhibit immune cell responses, hampering tumor clearance and control." (PMID 37686309, 2023). "TAMs directly or indirectly suppress the function of tumor-infiltrating CD8-positive T cells, secrete IL-10 cytokines to trigger immunosuppression, and support tumor cell proliferation and metastasis by promoting angiogenesis and ECM deposition." (PMID 37563723, 2023). "TAMs exert their effects on tumor cells through the production of enzymatic activities and cytokines such as interleukin-10 (IL-10) and transforming growth factor b (TGF-b)." (PMID 37152280, 2023). "We therefore analyzed the relationship between the levels of IL-6, IL-8 and IL-10 cytokines in the serum and tumor tissues, and the molecular subtypes of dogs with canine mammary gland tumors (CMGTs)." (PMID 36693957, 2023). "IL-10 and macrophage colony stimulating factor (M-CSF) secreted by tumor cells can also promote the migration of macrophages to tumor sites." (PMID 36902024, 2023).
tumor (continued). "The present study aimed to investigate the expression of serum/tissue IL-6, IL-8 and IL-10 in canine mammary gland tumors using Enzyme linked immunosorbent assay(ELISA), Western blot and Immunohistochemistry assay(IHC) to determine whether it is associated with tumor progression." (PMID 36693957, 2023). "By reducing IL-10 levels, SJ-C1044 counteracts the immunosuppressive tumor microenvironment, facilitating an immune response against the tumor." (PMID 37504287, 2023). "Some studies indicate that IL-10 positively contributes to tumor growth, whereas others have found that it contributes to the eradication and suppression of angiogenesis and metastasis, which are necessary for longer survival." (PMID 37533789, 2023). "Tumor-infiltrating Tregs mainly secrete IL-10 and TGF-β, both of which are key inhibitors of CD8+ T-cell function." (PMID 36831649, 2023). "We observed that IL-10 and IL-18 expression in tumor tissue was significantly decreased in the DEX-treated group compared with the saline-treated group." (PMID 37528154, 2023). "IL-10 signaling blockade has been shown to enhance vaccine-induced T cell responses and prevent tumor growth." (PMID 38011277, 2023). "Tumor growth was enhanced by IL-4 plus IL-10-stimulated macrophage CM, and tumor growth was more obvious in cells mixed with CM derived from miR-146b−/− macrophages." (PMID 37402945, 2023). "Among these cancer types, tumor-associated macrophage (TAM) markers such as CCL2, CD68, CD80, and IL10 had strong or moderate correlations with NNMT expression." (PMID 36817086, 2023). "IL-10 can stimulate pro-tumor neutrophils to produce PD-L2, which inhibits T cells, while IL-6 can enhance this process." (PMID 37496019, 2023). "Tregs are considered as tumor-promoting cells because of suppressing anti-tumor Teffs response by releasing inhibitory cytokines such as IL-10, TGF-β, and IL-35." (PMID 36891151, 2023). "Reduced levels of M2 macrophages are associated with reduced immune suppressive factors, including transforming growth factor-beta (TGF-β) and interleukin-10 (IL-10), and therefore tumour cells are able to evade immune responses." (PMID 37685898, 2023). "The immunosuppressive factors in the TME of PAAD, such as TGF-β and IL-10, can stimulate macrophages to differentiate into M2 macrophages with protumor effects and lead to a decrease in M1 macrophages with tumor-suppressor effects." (PMID 36782176, 2023). "Tregs suppress anti-tumor immune responses via the secretion of IL-10 and the sequestration of IL-2, and the infiltration of a large quantity of Tregs is often connected with a poor prognosis." (PMID 37345110, 2023). "M1 macrophages induced by cytokines, such as transforming growth factor (TGF)-β, interleukin (IL)-6, and IL-10, have anti-tumor activity." (PMID 36693070, 2023). "Tregs secrete anti-inflammatory cytokines including TGF-β, IL-10, and IL-35 into the microenvironment, and thereby suppress the activity of effector immune cells and consequently anti-tumor immunity." (PMID 37958417, 2023). "Taken together, WCP exerted its anti-tumor effects probably through the Cyto-c/Caspase8/3 and IL-10/STAT3/Bcl2 pathway in H22-tumor-bearing mice." (PMID 37110586, 2023). "MDSCs and M2 populations in PDAC also contribute to the secretion of arginase, nitric oxide synthase, IL-10, and TGFβ, which drives tumor invasion/growth and inhibition of antitumoral responses from NK and T cells." (PMID 37834100, 2023). "Though, tumor and tumor associated stromal cells secrete all these cytokines in a great extent, we found MDSCs are the major contributors in releasing IL-10, IL-6 and IL-1β over tumor cells itself." (PMID 38304256, 2023). "The results showed that the presence of B10 cells in the spleen and tumors of BAFF KO tumor-bearing mice was significantly lower than that in WT mice accompanied with a weakened ability of secreting IL-10." (PMID 35725835, 2023).
tumor (continued). "In contrast, other studies reported that IL-10 expression was significantly higher in ER+ tumor specimens." (PMID 37894728, 2023). "In this context, cytokines secreted from tumor and stroma cells, such as IL-10, as well as chemokines like CCL4, play a crucial role in shaping the immune TME in a tumor-promoting manner." (PMID 36982422, 2023). "Regulatory T cells promote tumor growth mainly by inhibiting T cell-mediated elimination of tumor cells through secretion of IL-10 and/or TGF-β." (PMID 38137433, 2023). "This decrease induces tumor-promoting Treg differentiation and increases production of the anti-inflammatory cytokine IL-10 in HNSCC, which is favorable to cancer progression." (PMID 37024932, 2023). "HMGB1 released from irradiated breast cancer cells stimulated M1-type macrophages to secrete high levels of TNF-α and low levels of IL-10, facilitating drastic anti-tumor activity." (PMID 37833255, 2023). "Other reviews have also indicated that inflammatory cytokines, such as interleukin(IL)-1, IL-6, IL-10, tumor necrosis factor-α, macrophage migration inhibitory factor, and transforming growth factor-β, are involved in tumor initiation and progression." (PMID 36855430, 2023). "IL-10 participates in tumor immune escape by inducing the activation of IL-10–dependent regulatory B cells." (PMID 37971595, 2023). "When anti-IL-10 blocking antibodies were exposed to tumor slices, they found significant tumor kill that was mediated by the reactivation of endogenous antitumor T cells." (PMID 37849667, 2023). "The mRNA expression of IL-10 and IL-18 in tumor tissues was assessed by quantitative polymerase chain reaction (qPCR)." (PMID 37528154, 2023). "By interacting with PD-1 receptors on the surface of T cells, PD-L1 on the surface of tumor cells can induce the death of activated T cells and boost IL-10 production in human peripheral blood, thereby promoting immunosuppression and tumor progression." (PMID 37056391, 2023). "We chose this specific tumor type based on our previous study that its homogenate most potently induced IL‐10 secretion in murine BMDMs and type I collagen production in mouse embryonic fibroblasts (MEFs), compared with homogenates from other tumor models." (PMID 36541165, 2023). "On the other hand, M2-polarized macrophages, driven by M-CSF, TGF-B, IL-4, IL-10 and IL-13, are believed to promote wound healing, angiogenesis and tumor growth by producing tumor growth factor (TGF)-β, IL-10, CCL17, CCL18, CCL22, CD206, CD204 and CD163." (PMID 37372147, 2023). "Both IL-2 and IL-10 were found to increase the anti-tumor cytotoxic activity of CD8+ T cells in vitro and a potential synergistic effect for the two cytokines." (PMID 37520880, 2023). "Following interaction with PD-L1 and PD-L2, PD-1 inhibits T cells mediated immune responses and subsequently induces IL-10 production by the tumor." (PMID 36810098, 2023). "Our findings demonstrate that oral administration of M13–NL prevents tumor development in AOM-exposed IL10−/− mice, suggesting that M13–NL is a promising oral drug formulation for preventing CAC." (PMID 37765299, 2023). "Upon Treg cell depletion, CCR8+ Tconv cells undergo systemic and intratumoral activation and expansion, and mediate IL-10 dependent suppression of anti-tumor immunity." (PMID 38100544, 2023). "At the same time, it reduces anti-tumor dendritic cells (DC), which leads to the synthesis and release of IL-10, inhibits immune response, leads to the synthesis and release of VEGF, and promotes angiogenesis." (PMID 36900158, 2023). "For instance, the MAPK signaling pathway inhibits the activity of immune cells in the tumor microenvironment by up-regulating the release of IL-6/IL-10 and other cytokines." (PMID 36982415, 2023). "IL-4 released by Th2 cells and the production of IL-4, IL-10, or IL-13 by tumor cells polarize macrophages into an M2 phenotype." (PMID 36761751, 2023).